TLR4 (toll like receptor 4)
Diseases named in the same sentence as TLR4 in open-access papers (continued):
Sharing a sentence is not in itself a finding about the gene and the disease.
infection (continued). "Moreover, when we then did infections, the lxpP mutant triggered less of a cytokine response than did the wild type, and this difference was lost upon exposure to TLR4 KO macrophages." (PMID 34280250, 2021). "In our present study, we confirmed that TLR signaling-related genes, including Tlr4, Nfkb, Myd88, Cd14, Il6 and Tnf, are gradually increased in the AP mouse model following induction of the infection and become highly expressed when lesion formation accompanied by bone destruction is established." (PMID 33510341, 2021). "Several studies have previously demonstrated that the activation of TLR2 and TLR4, as well as the subsequent activation of transcription factors leading to the production of inflammatory molecules, are important in the control of infection by various Leishmania spp." (PMID 34691019, 2021). "Similar changes were also seen in TNF-α levels in TLR4 −/− mice, which may be due to the complexity of the inflammatory response network after infection." (PMID 32098158, 2020). "Lactoferrin induces proinflammatory cytokine production after Bt infection that may be TLR4 dependent." (PMID 32764765, 2020). "Upon infection with that specific leptospiral strain, TLR4 was shown to be essential to the resolution of the infection, and authors described a TLR4-dependent iNOS activation that they hypothesize could contribute to the leptospiral clearance in mice." (PMID 32790743, 2020). "In fact, C. jejuni induced intestinal pro-inflammatory immune responses TLR4-dependently in secondary abiotic wildtype mice on day 14 post-infection, which also held true for secondary abiotic IL10-/- mice suffering from acute enterocolitis on day 6 upon C. jejuni challenge." (PMID 32443576, 2020). "While in the colon and duodenum the luminal C. coli loads were comparable, the pathogen burdens were approximately two and even four log orders of magnitude higher in the ileum and stomach, respectively, in TLR4-deficient IL10-/- as compared to IL10-/- counterparts, on day 21 post-infection." (PMID 32443576, 2020). "Meanwhile, we also assume that the decreased level of TLR2 and TLR4 in both spleen and MLNs could be considered as a result from L. salivarius improving intestinal barrier after infection since the pathogens leaked from lumen might be reduced." (PMID 33392276, 2020). "Moreover, L. donovani has devised mechanisms to alter the TLR4 signaling pathway to favor establishment of infection." (PMID 32210480, 2020). "Collectively, our data suggest that phloretin treatment protects macrophages from infection of virulent E. coli K1 strain by downregulating the TLR4-mediated signaling pathway and inhibiting NO and cytokine production, eventually protecting macrophages from E. coli-induced inflammation." (PMID 31893612, 2020). "Given the increased Th1 response observed in infected Tlr4-/- mice and the biphasic induction of Tlr4 mRNA in the spleen at 48 h and 6 wpi, we characterized both the number and the activation profile of DCs at different stages of infection: early (i.e., 48 h postinfection) and late (6 wpi)." (PMID 32210480, 2020). "From an evolutionary perspective, the potential of TLR4 to sense and integrate signals of fetal organ maturation, infection, and tissue damage and senescence confers the benefit of initiating birth when in utero conditions are unfavorable for continued fetal development and viability." (PMID 32313651, 2020). "MyD88, TLR2, TLR3, and TLR4 peak at 48, 24, 12, and 36 h after infection." (PMID 31947624, 2020). "Additionally, we observed a significant increase in TLR4 expression in the heart of immunocompetent mice at the beginning of infection, followed by a statistically significant reduction at 16 dpi." (PMID 32958053, 2020). "Hence, TLR4 signaling was involved in mediating C. coli-induced colonic histopathological and epithelial cell apoptosis upon peroral infection of secondary abiotic IL-10−/− mice." (PMID 33261211, 2020).
infection (continued). "However, co-inoculation with Tn5A7 resulted in enhanced clearance of WT infection in both TLR4-/- and TLR9-/- mice, indicating that neither TLR4 nor TLR9 signaling is required for differential recognition of kanamycin-propagated A. baumannii by the host." (PMID 32168364, 2020). "Although a differential spatial distribution was observed, the ubiquitous expression of TLR4 supports the idea that the male reproductive tract is an aseptic site in an active surveillance state and that TLR4 plays a primary role in the immune response to an infection." (PMID 32064024, 2020). "Therefore, we treated DCs with a combination of α-TLR2 and α-TLR4 blocking antibodies prior to infection and monitored subsequent expression of SOCS proteins." (PMID 33023610, 2020). "The role of the two TLR4 SNPs has been largely investigated in many diseases, with genetic association to some infection-related susceptibility, such as Gram-negative caused diseases and septic shock or to inflammatory diseases susceptibility, such as Crohn’s." (PMID 32349318, 2020). "Therefore, this study demonstrates for the first time that neutrophil activation during F. pedrosoi is conidial or hyphal-specific with TLR-2 and TLR-4 being essential during conidial infection but unnecessary for hyphal killing by neutrophils." (PMID 33193308, 2020). "Moreover, when evaluating DCs obtained from a mouse with a silenced TLR4 and infected with hMPV, the cytokines induced by the infection, such as IL-6, IL-10, CCL5, and IFN-β, were also decreased." (PMID 32765522, 2020). "Meanwhile, TREM2 knockdown enhanced the mRNA expression of TLR4 at the early stage of infection." (PMID 32401783, 2020). "However, the release of exosomes by gastroendothelial cells was stimulated by infection with the protozoan parasite Cryptosporidium parvum, in a process involving TLR4/IKK2 signalling and a SNAP23-dependent exocytosis." (PMID 32944186, 2020). "Therefore, our data demonstrate that TLR-2 and TLR-4 are indirectly associated with neutrophil migration because the lower levels of CXCL1 and CCL3 in KO animals’ infection site led to an impairment in neutrophil migration." (PMID 33193308, 2020). "Several studies also demonstrated that FA may target Toll-like receptor 4 (TLR4) to inhibit LPS infection." (PMID 32308620, 2020). "Moreover, the lung cytokine profile and the production of ROS were less affected by infection in MyD88–/– mice than in TLR4–/– mice, although these responses were weaker than in infected WT mice." (PMID 33042124, 2020). "In this report, we demonstrated, at a transcriptional level, the activation of human neutrophils in response to this infection, which could correspond to a significant expression of TLR4." (PMID 33253325, 2020). "Therefore, the strength of TLR2 and TLR4 agonists in M1 macrophage polarization should be evaluated carefully in host resistance within each infection model." (PMID 33304649, 2020). "TLR4 has been identified as an attractive target for immunomodulation because of its increased expression on infiltrating immune cells and multifaceted roles during infection." (PMID 30689633, 2019). "Interestingly, regarding the innate immune receptors associated with IL-12 response during several infections, the extracellular leucine-rich repeat domains of TLR2 and TLR4 contain four and nine N-glycans, respectively." (PMID 31226171, 2019). "This suggests that after corneal injury, NGF may promote expression of TLR4 in anticipation of a potential infection." (PMID 30599086, 2019). "TLR4 is an important molecule of the innate immune response on the host membrane that initially tries to prevent the entry of pathogens by generating a robust anti-inflammatory immune response and thereby prevent successful establishment of infection." (PMID 31649671, 2019).
infection (continued). "Therefore, the anti-inflammatory effect of Danshen root is partly due to the blocking of TLR4 dimerization, which can be used in clinical treatment of liver injury and infection during the anticancer strategies." (PMID 31061667, 2019). "The expression of TLR4 in RAW264.7 cells was upregulated after Salmonella CVCC541 infection, which could be effectively inhibited by JH-3 treatment, demonstrating a connection between JH-3 and TLR4, although the associated mechanism remains unclear." (PMID 30736473, 2019). "Furthermore, a recent study has shown that RSV activation of p38 in mitogen-activated protein kinase pathways (MAPKs) in a TLR4 mediated manner during the early stage of infection, utilized p38 to enter the cell for replication." (PMID 31417879, 2019). "TLR4 haplotype GCAG [p = 0.0035, OR = 0.44 (0.20–0.96)] was associated with the decreased risk whereas TLR9 haplotype GATC [p = 0.018, OR = 4.15 (1.16–14.80)] was associated with the increased risk of acquiring HPV 16 and 18 infection compared with controls." (PMID 31278284, 2019). "Some Salmonella serovars are capable of surviving within lymph nodes and it has been suggested that the host immune response to Salmonella LPS via TLR4 results in disruption of lymph node architecture 24 h after infection aiding the evasion of adaptive immune responses." (PMID 31771636, 2019). "Pellino-1 knockout mice develop normally but are protected from the adverse effects of systemic administration of TLR3 and TLR4 agonists, and Pellino-1 is shown to mediate endotoxin tolerance, further supporting its importance in infection-related inflammation." (PMID 31417543, 2019). "This showed that TLR4 in the fetal compartment was protective for the litter, whereas having it in the maternal compartment was harmful, a conflict which is yet to be investigated in other infections." (PMID 31178840, 2019). "TLR4 rs4986790, rs1927911 and TLR9 rs187084 showed association with HPV 16/18 infection." (PMID 31278284, 2019). "Further, data from the response following administration of living bacteria, either intravenously or as a localized infection, could be incorporated to model how such a cytokine response differs from the fixed TLR-4 response presented here." (PMID 30789941, 2019). "Yersinia pestis bacteria engineered to express hexaacylated lipid A during mammalian infection were significantly attenuated and subject to clearance by TLR4 and the NLRP12 inflammasome, suggesting that hypoacylation of lipid A renders these host defense mechanisms useless." (PMID 30642901, 2019). "The intensity of TLR4 expression increased with the duration of infection." (PMID 31309100, 2019). "Similarly, in our murine experiments, we noted that TLR9 gene expression is increased in lung leukocytes obtained by collagenase digestion and ficoll density separation 5 days post-PR8 infection while TLR4 is reduced." (PMID 30682165, 2019). "Western blot experiment results showed that, at the 3rd and 7th days after infection, protein expression levels of TLR4, TLR7, MyD88 and NF-κB p65 in the murine lung tissues of the control infected group were significantly higher than those in the control uninfected group (all P < 0.01)." (PMID 31551774, 2019). "Similarly, in the current study, the infection of E. coli O78 significantly increased the expression of TLR4 and NF-κB 3 and 7 days post-infection." (PMID 29948799, 2019). "Interestingly, NOD mice, which were the least efficient in clearing the infection, presented much more Marginal Zone B counts and also enhanced TLR4 expression on Marginal Zone B cells when compared to B6 and BALB/c mice." (PMID 30881362, 2019). "TLR4 plays an essential role in promoting inflammatory response to LPS infection in CD38−/− mice." (PMID 30915370, 2019).
infection (continued). "Although we have not evaluated the involvement of other receptors besides TLRs, our data indicate that TLR2 and TLR4 might play essential roles in the modulation of PMN functions by gp43 during an active infection." (PMID 31886295, 2019). "Additionally, we evaluate the expression of TLR2 and TLR4 after 24 h of infection and the expression of these receptors was similar to that obtained after 4 h of infection." (PMID 31119102, 2019). "Additionally, it has demonstrated that LPS treatment not only affected immune cells such as T cells and macrophage, but also had an impact on many types of epithelial cells through TLR4 signaling, which led to local infections or inflammatory processes." (PMID 30979040, 2019). "However, preclinical studies have shown the potential of combining anti-TLR2 and TLR4 antibodies with antibiotics to reduce inflammation whilst controlling infection." (PMID 30538643, 2018). "The impact of TLR4 on pregnancy outcomes was ascertained by comparing the proportions of abnormal stillbirths and individual fetus weights of the different maternal-fetal genotype combinations, 5 days after infection." (PMID 29440369, 2018). "MyD88, TLR2, and TLR4 regulated miRNA expression, such as let-7e, during the course of infection." (PMID 30555476, 2018). "Therefore, the activation of these cell signaling pathways after TLR4 engagement results in gene transcription and a cascade of inflammatory responses that initiate antimicrobial responses at the site of infection or inflammation." (PMID 29928275, 2018). "We next asked whether the protection afforded by fetal TLR4 could be attributed to alterations in the course of infection in the placenta." (PMID 29440369, 2018). "Interestingly, the diminished IL-8 responsiveness of COPD alveolar macrophage to NTHi infection has a strong association with the carriage of TLR9 (T1237C) polymorphism instead of TLR2 (Arg753Gln), TLR4 (Thr399Ile; Asp299Gly), and TLR9 (T1486C)." (PMID 30455693, 2018). "We propose that the high accumulation of both antimicrobial molecules might also be the consequence of the increased amounts of E. coli during the infection and inflammation, and its potential to stimulate TLR4 than only the inflammatory conditions." (PMID 30283451, 2018). "TLR4 signaling following Mollicutes infections is poorly described." (PMID 30050519, 2018). "TLR4, the most studied, has evolved as the receptor that responds to pathogenic infection, specifically LPS from Gram-negative bacteria." (PMID 29636723, 2018). "Treatment of mature sterile VEC multilayers with a low or high dose of the agonists or the DPBS vehicle control for 2 h before apical infection with ZIKV produced a modest reduction in ZIKV titers that was dose dependent when low dose LPS (TLR4) or FLAG (TLR 5) were compared to high dose treatments." (PMID 30692980, 2018). "We hypothesized that TLR4 might play a role in epithelial cell response to pathogens infection, and further studies would be focused on the relationship between TLR4 and HSV-2 infection in human genital epithelial cells." (PMID 30419930, 2018). "TLR4 (miR-146) has been reported to attenuate influenza virus infection with TLR4 antagonists, which may be a novel therapeutic approach to combat infection." (PMID 29556219, 2018). "Interaction of HMGB1 and TLR4 is involved in infection, tissue injury, and cancer." (PMID 30292233, 2018). "A similar decrease in the number of DC progenitors was recently described in a model of systemic Y. enterocolitica infection; the authors showed that infection favoured monopoiesis at the expense of DC differentiation in a Toll-like receptor 4 and IFN-γ-dependent manner." (PMID 30372491, 2018). "Our study supports the hypothesis of a Notch-transduced amplification of inflammation during infection as it reveals a gain of TLR4-primed and NF-κB -mediated expression of IL-6 and TNFα through Notch activation." (PMID 30042932, 2018).
infection (continued). "By detecting extracellular T. cruzi through TLR2 and TLR4 at the moment of the infection, or intracellular T. cruzi through TLR9 and TLR7, the cardiomyocytes should activate the MyD88 pathway and induce CCL5 that will focus the recruitment of cytotoxic CD8+ T cells towards the infected cell." (PMID 30067739, 2018). "HSV-2-infection enhance TLR4 mRNA transcription in a time-dependent manner in both cell lines." (PMID 30419930, 2018). "The TLR-4 response plays a significant role in fighting infection but may also be responsible for the dysregulated inflammation seen in septic shock." (PMID 30390640, 2018). "Furthermore, it was found that TLR4 and nucleolin levels increased early after infection and decreased subsequently, whereas TLR3 and TLR7 expression increased throughout RSV infection." (PMID 29427996, 2018). "As an answer to these questions, the infection of mice deficient for Toll-like receptor 2 (TLR2), TLR4, IL-10, arachidonate 5-lipoxygenase (ALOX5), or arachidonate 15-lipoxygenase (ALOX15) with the M. tuberculosis Δnrp strain showed the same phenotype as WT mice." (PMID 30381350, 2018). "Based on previous observations of a less severe inflammatory response in TLR4−/− mice, we hypothesized that the retinal gene expression profile would be significantly different between TLR4-deficient mice and C57BL/6 J mice following infection." (PMID 29661181, 2018). "Increased fetal death rates, preterm delivery rates, and fetal weight loss were observed in wild-type (WT) but not in Tlr4−/− primigravid females exposed to infections by different bacterial species." (PMID 29440369, 2018). "TLR4 has been shown to be involved in recognition of M. tb during infection." (PMID 29433383, 2018). "These immune evasion strategies involve TLR2 and TLR4, which are PRRs present on the surface of many cell populations, suggesting that the extracellular step could be critical for successful infection." (PMID 30532257, 2018). "Masson’s trichrome staining showed that collagen depositions were significantly increased both in TLR4 wild (P < 0.01) and TLR4 mutation mice (P < 0.05) on day 28 post-infection (p.i.), compared with no-infected mice." (PMID 28634394, 2017). "Our results demonstrated that infection with S. mitis together with P. aeruginosa could alleviate lung inflammation in acute lung infection mouse models possibly via the TLR4 signaling pathway." (PMID 28376744, 2017). "Based on the available data about the role of TLR4 in the infection with hRSV, it has been hypothesized that in the beginning, surfactant protein A-opsonized hRSV can bind to TLR4 expressed on the surface of alveolar epithelial cells and AMs." (PMID 29230219, 2017). "Since malaria infection did not cause changes in the placental tissue in TLR4−/− mice, we hypothesized that the infection leads to an inflammatory state, which is dependent on the TLR4 activation." (PMID 28819109, 2017). "We further examined the gene expression of pro-inflammatory chemokines (CXCL1, CXCL2 and CCL2), chemokine receptor CCR7, and TLR4 in lung tissues in order to determine the potential mechanism(s) of immune cells infiltration into the lungs of newborns following low dose infection with B. pertussis." (PMID 28798335, 2017). "Infection Index assays showed that TLR4 also plays a role in L. amazonensis infection." (PMID 29213084, 2017). "We examined whether TGM2 might not only act downstream of TLR4 signaling but also act as an upstream activator of the TLR4 signal pathway in our infection model." (PMID 29321784, 2017). "While the TLR4 ligand in strain BTB 02-171 remains to be identified, these observations invite speculation that TLR4 signaling in this context may occur from maturing mycobacteria-containing phagosomes or endosomal compartments during infection." (PMID 29230217, 2017). "ECTV-infection significantly (P > 0.01) inhibited TLR4 agonist + ATP-induced IL-18 production." (PMID 29312229, 2017).